IL9 (interleukin 9)
Diseases named in the same sentence as IL9 in open-access papers (continued):
Sharing a sentence is not in itself a finding about the gene and the disease.
pancreatic cancer (4 papers, 2016 to 2022). "Therefore, this study aimed to investigate the role of the interaction between IL-9 and miR-200a in the modulation of pancreatic cancer progression in order to elucidate the underlying molecular mechanisms." (PMID 28349057, 2017). "And a targeted blockade of IL9 led to a restrained tumor growth in a murine model of pancreatic cancer." (PMID 36131941, 2022). "In the past, preclinical results from cell experiments described IL9 as a tumor-supportive cytokine promoting proliferation and metastasis in pancreatic cancer cells." (PMID 36131941, 2022). "As a lymphocyte growth factor, IL-9 can promote the deterioration of hematological neoplasms, and it is worth noting that IL-9 can also promote the growth of some solid tumors, such as pancreatic cancer and CAC." (PMID 32228589, 2020). "It has been reported that IL-9 can promote the proliferation and migration of pancreatic cancer cells through the miR-200a/β-catenin axis." (PMID 32228589, 2020). "IL-9 can reverse this phenomenon, which can reduce the expression of miR-200a on pancreatic cancer cells, thus promoting the development of pancreatic cancer." (PMID 32228589, 2020). "Treatment of pancreatic cancer cells with IL-9 decreased miR-200a expression and increased β-catenin expression; the effect of miR-200a on pancreatic cancer cells was reduced by IL-9 treatment." (PMID 28349057, 2017). "Pancreatic cancer cells (PANC-1 and AsPC-1) were treated with IL-9 and the expression of miR-200a and β-catenin in pancreatic cancer cells was measured." (PMID 28349057, 2017). "IL-9 significantly promoted the proliferation, invasion, and migration of pancreatic cancer cells; however, the effect on pancreatic cancer cell apoptosis was insignificant." (PMID 28349057, 2017). "IL-9 treatment of pancreatic cancer cells decreased miR-200a expression and increased β-catenin expression." (PMID 28349057, 2017). "First, only the PANC-1 and AsPC-1 cells lines were used to explore the effect of IL-9 on pancreatic cancer cells and the interaction between IL-9 and miR-200a." (PMID 28349057, 2017). "The results showed that the effect of inhibition of miR-200a on pancreatic cancer cells was promoted following IL-9 treatment." (PMID 28349057, 2017). "Our results provide preliminary information regarding the role of the interaction between IL-9 and miR-200a in the regulation of pancreatic cancer cells." (PMID 28349057, 2017). "In the present study, we show that IL-9 promotes pancreatic cancer cell proliferation and metastasis and that this effect might occur via the miR-200a/β-catenin axis." (PMID 28349057, 2017). "IL-9 promotes proliferation and metastasis in pancreatic cancer cells; this effect may partly involve regulation of the miR-200a/β-catenin axis." (PMID 28349057, 2017). "Moreover, IL-9 decreased miR-200a expression and increased β-catenin expression even following miR-200a mimics infection, suggesting that the effect of IL-9 on pancreatic cancer cells may occur through the miR-200a/β-catenin axis." (PMID 28349057, 2017). "Thus, anti-IL-9 could be used as a novel potential approach in the treatment of pancreatic cancer metastasis." (PMID 28349057, 2017). "In addition, we also observed that IL-9 has a little effect on pancreatic cancer cell apoptosis." (PMID 28349057, 2017). "Pancreatic cancer cells (PANC-1 and AsPC-1 cells) were treated with 0, 10, 20, or 40 ng/ml IL-9 for 48 h." (PMID 28349057, 2017). "In order to examine the interaction between IL-9 and miR-200a in pancreatic cancer cells, PANC-1 and AsPC-1 cells were treated with IL-9 at different concentration, and the expression of miR-200a was decreased with the elevation of IL-9 concentration." (PMID 28349057, 2017).
respiratory syncytial virus infection (4 papers, 2018 to 2025). "In addition, IL-9 has been shown to modulate immune responses during respiratory syncytial virus infection, and play protective roles against Helicobacter pylori and parasitic worm infections." (PMID 35795670, 2022).
type 1 diabetes (4 papers, 2014 to 2022). "We observed that in case children, several SFAs and CLA were associated with many immunological markers [CXCL10 (IP-10), IL-6, IL-9, IL-17, and CM-CSF] that have been linked to the development of type 1 diabetes." (PMID 35693790, 2022). "The role of Th17 plasticity in the development of type 1 diabetes was further implicated by the observation that TGF-β induced secretion of IL-9 in Th17 cells in children with recent-onset type 1 diabetes." (PMID 35693790, 2022). "In cases, SFAs were associated with several immunological markers (CXCL10, IL-6, IL-9, IL-17, and CM-CSF) previously linked to the type 1 diabetes disease process." (PMID 35693790, 2022). "IL-9 is associated with podocyte injury in early type 1 diabetes, and there are complex interactions between urinary IL-9, inflammatory cytokines and ACR." (PMID 35445345, 2022). "In our study, DMA18 also correlated inversely in case children at 6 months of age with IL-9 and GM-CSF, i.e., cytokines that have been linked to type 1 diabetes." (PMID 35693790, 2022). "In turn, in case children at the age of 6 months, n-6 LA and AA were directly associated with cytokines (IL-6, IL-9, and CXCL10), which have been previously linked to pre-clinical and clinical type 1 diabetes." (PMID 35693790, 2022). "We sought to relate urinary IL-9 levels to the release of podocyte-derived extracellular vesicles (EVs) in youth with type 1 diabetes." (PMID 35445345, 2022). "Moreover, production of Th9 (IL-9) and Th17 (IL-17A) cytokines by T cells from control subjects and type 1 diabetes donors were reduced after exposure to 1,25(OH)2D3 or TX527." (PMID 25279717, 2014).
acute coronary syndrome (3 papers, 2019 to 2024). Signs and symptoms related to acute ischemia of the myocardium secondary to coronary artery disease. "Levels of IL-9 have also been reported to be elevated in patients with acute coronary syndrome and in patients with carotid artery stenosis." (PMID 39091640, 2024). "Another study revealed a significant increase in the number of peripheral Th22 cells and the protein levels of IL-22 and IL-9 in patients with acute coronary syndromes compared with those in the stable angina pectoris and control groups." (PMID 31011288, 2019).
age-related macular degeneration (3 papers, 2021 to 2024). Age-related loss of vision in the central portion of the retina (macula), secondary to retinal degeneration. "In addition, IL9 haplotype analysis also revealed an association of the rs2069885 polymorphism with a predisposition to age-related macular degeneration (AMD)." (PMID 36361964, 2022).
angina (3 papers, 2013 to 2017). "IL-9 levels were significantly upregulated in patients with AMI compared with the stable angina pectoris and control groups." (PMID 28044128, 2016). "(iii) T cells and monocytes from patients with unstable angina (n = 17) had increased mRNA levels of IL-9 as compared with controls (n = 11)." (PMID 24023645, 2013). "(v) IL-9 increased IL-17 release in peripheral blood mononuclear cells from patients with unstable angina (n = 5) and healthy controls (n = 5) with a particularly enhancing effect in cells from the patient group." (PMID 24023645, 2013). "In fact, while IL-9 seemed to suppress IL-17 release in PBMCs from healthy controls, it enhanced IL-17 release in cells from unstable angina patients." (PMID 24023645, 2013). "To further examine the regulation of IL-9 in atherosclerotic disorders, we analyzed mRNA levels of IL-9 and IL-9R in T cells and monocytes from patients with stable and unstable angina and in healthy controls." (PMID 24023645, 2013). "These new findings further underscore a link between IL-9 and IL-17 and suggest that this link is particularly strong in patients with unstable angina, potentially reflecting up-regulation of IL-9R in T cells from these patients." (PMID 24023645, 2013). "Finally, enhanced expression was also seen at the cellular level with increased levels of IL-9 mRNA and IL-9R in T cells from patients with unstable angina, and for IL-9, this up-regulation was also seen in monocytes." (PMID 24023645, 2013). "Indeed, in the present study we found that IL-9 promoted a IL-17 release in PBMCs, with a particularly marked response in cells from unstable angina patients." (PMID 24023645, 2013). "The same pattern was seen for IL-9 in monocytes with increased mRNA levels in unstable, but not in patients with stable angina compared to healthy controls." (PMID 24023645, 2013). "T cells from patients with unstable, but not stable angina had significantly increased mRNA expression of IL-9 and IL-9R compared with T cells from healthy controls, and for IL-9, the difference between unstable and stable disease was also significant." (PMID 24023645, 2013).
carotid atherosclerosis (3 papers, 2013 to 2015). A thickening and loss of elasticity of the walls of carotid arteries that occur with formation of atherosclerotic plaques. "IL-9 plasma levels were significantly raised in patients with carotid atherosclerosis compared with healthy controls (n = 28), and in patients admitted for acute ST-elevation myocardial infarction (STEMI)." (PMID 26544186, 2015). "Here we have examined IL-9 and IL-9 receptor (IL-9R) systemically and locally in patients with coronary and carotid atherosclerosis." (PMID 24023645, 2013). "However, the present study is, to the best of our knowledge, the first report of increased levels of IL-9 in patients with confirmed coronary and carotid atherosclerosis." (PMID 24023645, 2013). "Carotid lesion samples from patients with asymptomatic and symptomatic carotid atherosclerosis had markedly increased expression of IL-9 and IL-9R as compared with samples from non-atherosclerotic vessels (common iliac artery)." (PMID 24023645, 2013).
cervical cancer (3 papers, 2021 to 2024). A primary or metastatic malignant neoplasm involving the cervix. "These antitumor properties of IL-9 are promising in preventing metastasis and cervical cancer progression." (PMID 38256080, 2024). "IL-9, a T-helper 9 cytokine, reduced the expression of N-cadherin and vimentin in cervical cancer cells and increased expression of E-cadherin." (PMID 36766756, 2023). "In cervical cancer, IL-9 enhanced anti-tumor response through T cell cytotoxicity and controlled malignant cell transformation." (PMID 34177894, 2021). "Interestingly, IL-9, produced by T-helper 9 cells, was shown to downregulate N-cadherin and vimentin expression in cervical cancer while upregulating E-cadherin expression." (PMID 38256080, 2024). "Therefore, IL-9-based therapy has the potential to prevent progression and metastasis in cervical cancer." (PMID 36766756, 2023).
Chagas disease (3 papers, 2016 to 2023). A parasitic infection caused by Trypanosoma cruzi. "Data about the role of IL-9 in other pathologies are scarce and sometimes contradictory, and few studies have explored the influence of this cytokine on Chagas’ disease pathology." (PMID 34722343, 2021). "In vivo, Y strain TCTs stimulated the production of IL-9 in the heart and Th9 and Tc9 splenic cells in the chronic phase of Chagas’ disease." (PMID 34722343, 2021). "Data on the role of IL-9 in other pathologies are sometimes contradictory, and few studies have explored this cytokine’s influence in Chagas’ disease pathology." (PMID 34722343, 2021). "Interestingly, chronic phase also demonstrated elevated IL-6 serum levels in response to infection and also in heart lysates when neutralizing IL-9, probably these cytokines can interplay a fine tune between beneficial inflammation and tissue damage throughout Chagas’ disease." (PMID 34722343, 2021).
chronic heart failure (3 papers, 2011 to 2022). "Inflammation and inflammatory factors have been continuously concerned in the pathogenesis of cardiovascular disease; the plasma levels IL-9 was detected to be associated with cardiopulmonary dysfunction and all-cause mortality in chronic heart failure." (PMID 35087951, 2022). "Nevertheless, high plasma IL-9 levels are associated with poor treatment outcomes in HIV/HCV-coinfected patients and in patients with chronic heart failure." (PMID 24130824, 2013). "It is worth noting that our study, for the first time, has associated IL-5, IL-7, IL-9, and IFN-γ plasma levels with chronic heart failure." (PMID 21418620, 2011). "However, what was noteworthy, and described here for the first time, was the increase of IL-9, and decrease of IL-5, IL-7 and IFN-γ plasma levels in patients with chronic heart failure." (PMID 21418620, 2011). "Further studies are needed to assess whether the modification of IL-5, IL-7, IL-9 and IFN-γ plasma levels has a null, a protective, or a pathogenetic role in chronic heart failure and may constitute a potential target for therapeutic intervention." (PMID 21418620, 2011).
chronic obstructive pulmonary disease (3 papers, 2019 to 2022). A chronic and progressive lung disorder characterized by the loss of elasticity of the bronchial tree and the air sacs, destruction of the air sacs wall, thickening of the bronchial wall, and mucous accumulation in the bronchial tree. "In a mouse model of Chronic Obstructive Pulmonary Disease (COPD), IL-9 plays a role in aggravating the lung injury by increasing inflammatory and oxidative stress in a STAT3-dependent manner." (PMID 31035677, 2019).
Cirrhosis (3 papers, 2021 to 2024). A chronic disorder of the liver in which liver tissue becomes scarred and is partially replaced by regenerative nodules and fibrotic tissue resulting in loss of liver function. "There was no statistical difference of serum IL-9 level between HCC patients with and without cirrhosis (93.42 ± 9.46 pg/mL vs 98.50 ± 16.92 pg/mL, P=0.373, Student t test)." (PMID 34177894, 2021).
coronary artery disease (3 papers, 2016 to 2025). "Cholesterol levels are associated with two IL9 promoter SNPs, while coronary artery disease is associated with SNPs in the IL9 promoter and intronic noncoding regions." (PMID 38825637, 2024). "Despite previous investigations into the impact of the Mediterranean diet on IL-9 levels in various conditions such as ischemic heart disease and T2DM yielding no significant findings, our study revealed a statistically significant reduction in IL-9 levels at T2 compared with those at T0." (PMID 40362746, 2025).
endometrial carcinoma (3 papers, 2020 to 2025). A malignant tumor arising from the epithelium that lines the cavity of the uterine body. "This alignment across different sample types reinforces the potential of IL-9 as a diagnostic marker for endometrial cancer." (PMID 39334861, 2024). "Given the scarcity of data on these proteins in endometrial cancer, this study aims to evaluate the diagnostic potential of preoperative serum concentrations of IL-4, IL-7, IL-9, IL-10, NT, TSP-2, and NRP1." (PMID 39334861, 2024). "Studies on the impact of IL-9 on endometrial cancer have highlighted the significant infiltration of IL9+ cells and overexpression of IL9R tumor tissues." (PMID 39334861, 2024). "Nonetheless, further research is necessary to fully elucidate the mechanisms by which IL-9 contributes to endometrial cancer pathogenesis and to validate its use as a clinical biomarker." (PMID 39334861, 2024). "Interleukin-9 (IL9) plays a critical role in immunity and the pathogenesis of endometrial cancer (EC), especially endometrioid EC (EEC)." (PMID 33329510, 2020). "Our study aimed to determine whether IL-4, IL-7, IL-9, IL-10, NT, TSP-2, and NRP1 could be diagnostic markers for endometrial cancer in women." (PMID 39334861, 2024). "Besides, IL9R, the receptor of IL9, was up-regulated in the endometrium tissue and endometrial cancer tissues as well." (PMID 33329510, 2020). "IL-4, IL-7, IL-9, NT, and NRP1 may be useful diagnostic markers for endometrial cancer." (PMID 39334861, 2024). "The initial study presented here demonstrates the clinical utility of IL-4, IL-7, IL-9, NT, and NRP1 in endometrial cancer." (PMID 39334861, 2024). "This study suggests the clinical utility of IL-4, IL-7, IL-9, NT, and NRP1 in the diagnosis of endometrial cancer." (PMID 39334861, 2024). "The results revealed that IL-9 was also produced by Vδ2 T cell, ILC2, mast cells, eosinophils, M2 macrophages, TH9, and NK/NKT cells in the endometrial cancer tissues." (PMID 33329510, 2020). "Similar to IL9, IL9R RNA was also up-regulated in endometrial cancer tissues (UCEC) compared to adjacent normal tissues (n = 265, p < 0.05)." (PMID 33329510, 2020). "Finally, we evaluated the significance of IL-4, IL-7, IL-9, IL-10, NT, TSP-2, and NRP1 in the diagnosis of endometrial cancer." (PMID 39334861, 2024). "The purpose of this study was to determine if IL-4, IL-7, IL-9, IL-10, NT, TSP-2, and NRP1 could be used as novel, helpful markers for the detection of endometrial cancer." (PMID 39334861, 2024).
Granuloma (3 papers, 2017 to 2024). A compact, organized collection of mature mononuclear phagocytes, which may be but is not necessarily accompanied by accessory features such as necrosis. "(2016) observed the predominance of IL-9 in TT individuals, mainly in lymphocytic granulomas and granulomas composed of macrophages." (PMID 39308868, 2024). "In parallel with the development of egg granulomas, the hepatic levels of IL-9 and PU.1 increased very slowly during the first four weeks post-infection and increased rapidly thereafter." (PMID 28646920, 2017). "The time of IL-9+ Th9 cells’ peak in infected mouse liver was one week before the peak of the granuloma area in liver and cytokine level in serum and implied that IL-9 could mediate the pathogenic changes induced by S. japonicum." (PMID 28539607, 2017).
Graves disease (3 papers, 2021 to 2025). Graves' disease is an autoimmune disorder that leads to overactivity of the thyroid gland (hyperthyroidism).It is caused by an abnormal immune system response that causes the thyroid gland to produce too much thyroid hormones. "Serum cytokine levels (including IL-6, IL-9, IL-17A, IL-17F, and IL-22) exhibited significant differences between healthy subjects and patients with newly diagnosed hyperthyroid Graves’ disease (GD) under varying serum iodine concentration (SIC)." (PMID 40895623, 2025).
heart failure (3 papers, 2013 to 2022). Inability of the heart to pump blood at an adequate rate to meet tissue metabolic requirements. "Increased plasma levels of IL-9 are seen in patients with heart failure, possibly correlated to disease progression, and increased IL-9 levels have been reported in experimental cardiomyopathy." (PMID 24023645, 2013). "The concentrations of IL-5, IL-6 and IL-9 were significantly higher in the saliva of heart failure patients with both NS and HS compared to the control group, while IL-4 level was significantly higher only in heart failure patients with HS." (PMID 36300113, 2022).
immune deficiency (3 papers, 2013 to 2021). "For example, in a condition of immune deficiency of certain molecules or cells, IL-9 may become a replacement thus playing a compensatory role in host defense mechanisms." (PMID 25646821, 2015). "Since γc is shared by receptors for IL-4, IL-7, IL-9, IL-15, and IL-21 and a loss of γc function causes immunodeficiencies in both humans and mice, it is anticipated that knockdown of γc may lead to severe systemic side effects." (PMID 24223832, 2013).